IL6 (interleukin 6)
Diseases named in the same sentence as IL6 in open-access papers (continued):
Sharing a sentence is not in itself a finding about the gene and the disease.
Obesity (continued). "Obesity is associated with an increase in the level of IL-6, whereas weight loss leads to a decrease in its concentration." (PMID 34088886, 2021). "Obesity predisposes patients to a pro-inflammatory state via increased inflammatory mediators interleukin-6 (IL-6) and tumor necrosis factor-α (TNF-α), as well as reduced levels of adiponectin, which has a totally anti-inflammatory function." (PMID 33919190, 2021). "As a prime instance, overexpression of IL-6 can lead to complications such as dyslipidemia, which in turn, can cause obesity." (PMID 34830435, 2021). "The aim of this study was the investigation of the relationships between depression and obesity parameters as well as genetic traits, including IL-1 and IL-6 genetic polymorphisms." (PMID 34680892, 2021). "Exercise and adipose tissue are associated with elevated plasma concentrations of IL-6, which counteracts obesity, insulin resistance, and T2DM." (PMID 34327205, 2021). "Here, we asked if diet-induced obesity predisposition or protection is accompanied by differences in hypothalamic IL6 levels (described in “In vivo protocol #2”)." (PMID 34465367, 2021). "In obesity, the increase in leptin levels is associated with the state of leptin resistance, in addition to the increase in reactive oxygen species (ROS), IL-6, TNF-α, and chemokines." (PMID 33807959, 2021). "With respect to the immune response, there is a clear association between obesity and basal inflammatory status characterized by higher circulating Interleukin 6 and CRP levels." (PMID 33761466, 2021). "It has been described that proinflammatory cytokines such as tumor necrosis-alpha (TNF-α), interleukin (IL)-1β and IL-6 play a central role in cardiac damage associated with ischemic conditions and obesity, as well." (PMID 34439522, 2021). "There are discrepancies about the relationship of IL-6, clusterin and irisin with obesity and obesity associated insulin resistance and also about their sexual dimorphism." (PMID 33905632, 2021). "Obesity in both sexes, especially in males was associated with high levels of IL-6, clusterin and irisin and worsened the metabolic pattern." (PMID 33905632, 2021). "The enrichment of the Deferribacteres and Tenericutes population is a common phenomenon in obesity, which is positively linked with the pro-inflammatory factors IL-6, TNF-α, and IL-17A, causing aggravation of inflammation in obesity." (PMID 33585429, 2021). "A model encompassing also the interaction term “adiponectin*obesity” revealed the interaction term independently associated with IL-6 DNA methylation (Beta = −0.797; t = −2.134, p < 0.05)." (PMID 34869683, 2021). "IL-6 is one of the major pro-inflammatory factors released from adipose tissue and higher levels have also previously been associated with obesity as well as diseases like diabetes and asthma." (PMID 34059769, 2021). "For example, it has been observed that increased serum TNF- α and IL-6 levels but decreased levels of adiponectin and IL-10 are associated with increased inflammation, tissue injury and complications of obesity." (PMID 35601749, 2021). "Obesity is associated with elevated markers of peripheral inflammation such as CRP and IL-6, and CM is associated with increased risk of obesity." (PMID 33831008, 2021). "Many candidate genes and polymorphisms have been considered, including variants of the interleukin 6 (IL-6) genes, involved in inflammatory process and many other mechanisms related to obesity." (PMID 34680892, 2021). "This decrease of TNF-α and IL-6 can reduce the risk of insulin resistance in a population with obesity." (PMID 34948868, 2021). "Pro-inflammatory cytokines such as TNFα and IL6 are considered essential factors in developing obesity-associated IR68." (PMID 34417511, 2021).
Obesity (continued). "Obesity, independent from AF, has also been linked to systemic inflammation (elevated levels of C‐reactive protein, IL‐6 and tumor necrosis factor‐α [TNF‐α]), due to IL‐6 and TNF‐α production from (visceral) adipose tissue." (PMID 33769583, 2021). "As a result, obesity is associated with a low-grade chronic inflammation characterized by an increase in proinflammatory cytokines (IL-6, TNF-α, IL-1α) and a reduction in anti-inflammatory cytokines (IL-4, IL-10, and IL-13)." (PMID 34439950, 2021). "IL-6 is an interleukin that acts as both a pro-inflammatory cytokine and as a myokine involved in the development of obesity-associated insulin resistance." (PMID 34206780, 2021). "In colitis-associated colorectal cancer, signaling through obesity-induced IL-6 was reported to shift macrophage polarization towards a tumor-promoting phenotype that produced the chemokine CC-chemokine-ligand-20 (CCL-20) in the tumor microenvironment." (PMID 33987528, 2021). "Plasma levels of CRP and IL-6 correlated (r = −0.429) with the degree of obesity (r = 0.282) and suggested that IL-6 is associated with developing metabolic diseases." (PMID 33579000, 2021). "The subjects were divided into groups depending on the obesity parameters BMI (body mass index) and fat percentage (fat%), and the following IL-6 SNPs (Single Nucleotide Polymorphisms) were analyzed: rs1800795, rs1800796 and rs13306435." (PMID 34680892, 2021). "Obesity is associated with increased production of pro-inflammatory cytokines, such as IL-6 and TNFα, which are associated with cognitive decline." (PMID 33941254, 2021). "Several studies have evaluated the correlation of IL6 gene variants with indicators of obesity in humans, and the obtained data are contradictory." (PMID 34834553, 2021). "It is especially remarkable how both compounds are capable of reducing insulin resistance by lowering glycemia and plasma insulin concentrations as well as obesity-associated inflammatory markers such as IL-6 and TNF-α." (PMID 34444748, 2021). "Chicoric acid was found to reduce lipid peroxidation and increase the antioxidants activity and TAC in liver of mice and prevent inflammations of hepatic cells associated with obesity via decreasing the IL-6, TNF-α, and MPO activity." (PMID 34827094, 2021). "In fact, we showed that exogenous IL6 reduces body mass, whereas IL6 deficiency results in obesity predisposition." (PMID 34465367, 2021). "This is further supported by human studies that show both obesity-protection and obesity predisposition associated with different polymorphisms of the IL6 gene." (PMID 34465367, 2021). "Obesity-accelerated cancer growth is also associated with increased IL-6 levels and shift in M2/M1 macrophage ratio in a genetic mouse model of prostate cancer." (PMID 33987528, 2021). "This was mainly based on the observations that C-reactive protein (CPR) and interleukin-6 (IL-6) levels were increased in obesity, and that weight loss was associated with a decline in cytokine levels." (PMID 33604566, 2021). "Accumulating studies show elevated levels of plasma TNF-α and IL-6 in patients with obesity associated insulin resistance." (PMID 33917607, 2021). "Low-grade chronic inflammation, characterised by a higher concentration, in basal levels, of the pro-inflammatory cytokines TNF-α, IL-1β, monocyte chemoattractant protein-1 (MCP-1) and IL-6, is an obesity hallmark." (PMID 33183383, 2021). "Obesity-associated HCC development depended on the increased tumor-promoting cytokines IL-6 and TNF, inducing liver inflammation and activation of oncogenic signal transducer and activator of transcription 3 (STAT3) signaling in mice." (PMID 35002979, 2021). "Pregravid obesity disrupted pregnancy-associated monocyte activation, leading to a significantly reduced number of TNFα/IL-6 producing monocytes relative to lean subjects in response to LPS at T3." (PMID 34195568, 2021).
Obesity (continued). "Il6-deficiency in mice resulted in higher adipogenesis and obesity, which result from insufficient Arid5a induction." (PMID 35126382, 2021). "As obesity also causes low‐grade chronic inflammation, we investigated the expression of the inflammation markers Tnfα, Il‐1β, and Il‐6 in subcutaneous and epigonadal fat." (PMID 32537550, 2020). "Taken together, despite some protective anti-inflammatory effects of EPA and ACE-I combination, such as attenuating IL-6, the underlying mechanisms require further studies in both in vitro and in vivo models of obesity-induced breast cancer." (PMID 31963198, 2020). "MKO mice have significant reductions in circulating IL-6 levels, an adipocytokine associated with obesity-induced systemic inflammation insulin resistance." (PMID 32464603, 2020). "Psoriasis and obesity share common pathogenic mechanisms, i.e., increased production of pro-inflammatory cytokines (IL-1, IL-6, TNF-α, and adiponectin) which are responsible for a chronic low-grade inflammation which are observed in both conditions." (PMID 33187195, 2020). "Obesity is also associated with chronic low-grade inflammation, dysbiosis, and increased secretion of inflammatory cytokines, including interleukin 6 (IL-6)." (PMID 32574257, 2020). "IL-17, like IL-6, is strongly associated with progression towards insulin resistance and type 2 diabetes in individuals with obesity." (PMID 32027700, 2020). "This hypothalamic inflammatory signaling is typical in obese individuals fed a diet rich in lipids, which induces an increase in IL-6 and NF-κB gene expression, consequently causing neuronal death during obesity." (PMID 33080865, 2020). "Secretion of proinflammatory cytokines such as interleukin-6 and tumor necrosis factor-α from obesity-induced hypertrophic fat cells causes muscle atrophy." (PMID 33379405, 2020). "This aspect can be demonstrated by plasma IL-6 being elevated in obesity and diabetes, in addition to reduced levels in weight loss." (PMID 32265845, 2020). "Following bariatric surgery, obesity-associated systemic inflammation persists for as much as 1 month, as indicated by IL-6 and CRP levels." (PMID 32158768, 2020). "As in adiponectin production, adipose tissue plays an important role in the production of IL-6 and several studies have shown that obesity is associated with elevated IL-6 concentration in both PLWH as well as in the general population." (PMID 33238950, 2020). "Elevated levels of IL-6 accompany, for example, obesity and type 2 diabetes, and IL-6 is often linked with the metabolic syndrome, not least in animal models." (PMID 32393961, 2020). "Since obesity is associated with increased inflammatory markers, our objectives were to determine interleukin-6 (IL-6) levels in obese mice and to examine the effect of IL-6 on placental endothelial cells." (PMID 31979004, 2020). "On the other hand, obesity is associated with low-grade chronic inflammation, where the enlargement of adipocytes induces the secretion of TNFα and Il6, leading not only to insulin resistance but also to bone loss." (PMID 32664580, 2020). "A study in 123 patients and 46 age-matched controls reported the addition of reactive oxygen species, obesity, low adiponectin, and high glucose and interleukin-6 as cause of the abatement in Irak3 in THP-1 cells in vitro." (PMID 32351607, 2020). "For example, TNF secretion from adipose tissue and circulating plasma IL-6, both of which play a role in insulin-response, were highly associated with obesity-associated insulin resistance in a human cohort." (PMID 33287442, 2020). "Chronic inflammation is a hallmark of individuals with obesity, which includes elevated levels of IL‐6." (PMID 32845580, 2020). "In adolescents with obesity, the presence of periodontal pockets was associated with higher levels of IL-6 and raised diastolic blood pressure." (PMID 32850543, 2020).
Obesity (continued). "There are inflammatory mediators associated with obesity and T2D, such as inteleukin-6 (IL-6), IL-32, tumor necrosis factor – α (TNF-α), that have a direct effect on vascular wall and plaque formation, but they are not within the scope of this work." (PMID 32337369, 2020). "Despite high levels of IL-6 having been associated with obesity and T2D, IL-6 also exhibits anti-inflammatory effects during exercise." (PMID 32722013, 2020). "Obesity is also linked to a condition of chronic inflammation, mediated in particular by the cytokines IL-6 and TNF-α, expressed in adipose tissue." (PMID 33167396, 2020). "It has also been shown that localised high expression of tumour necrosis factor (TNF) and interleukin-6 (IL-6) are associated with obesity induced insulin insensitivity." (PMID 32015415, 2020). "In BAT, macrophage infiltration contributes to the high levels of inflammatory cytokines (TNF, IL-6, and IL-1β) in conditions associated with AT hypertrophy such as high fat diet or obesity." (PMID 32934774, 2020). "Obesity and increased levels of circulating interleukin-6 (IL-6) have been associated to the morbidity and mortality seen in Human immunodeficiency virus (HIV)." (PMID 33202598, 2020). "Obesity was shown to be associated with a decrease in circulating adiponectin and increased IL-6 and FFAs levels." (PMID 32120856, 2020). "On the other hand, in rodent models, high-fat diets and obesity have been shown to activate the hepatic inflammatory mediator, NF-κB, which cause hepatic inflammation by an increase in local inflammatory cytokine IL-6." (PMID 32420546, 2020). "In detail, an IL-6/Stat3-dependent formation on these NK cells seems to account to obesity-associated pathologies." (PMID 32231659, 2020). "WAT is one of the major sources of IL-6 in obese humans and mice, which is a key component of the low-grade systemic inflammation observed in overweight and obesity and is associated with insulin resistance." (PMID 32831895, 2020). "The non-reference allele frequency in this study was 0.084, which is similar to the non-reference allele frequency of 0.11 found in Polish Labrador retrievers (n = 136) in a study on the relation between polymorphisms in RETN, TNF and IL6 and obesity in dogs." (PMID 33142854, 2020). "To study the effects of eplerenone on chronic inflammation associated to obesity, we measured the mRNA levels of IL6, HSP90, and aP2." (PMID 32373073, 2020). "Obesity is associated with elevated circulating levels of IL-6 and TNFα, which are subsequently decreased with weight loss." (PMID 32158768, 2020). "For example, in animal studies, overexpression of IL-6 has been reported to reduce fat accumulation and weight gain, whereas IL-6-deficient mice develop mature-onset obesity." (PMID 32878032, 2020). "We next measured the mRNA expressions of tumor necrosis factor-α (Tnfa) and Il6, encoding cytokines that are considered to be important mediators of insulin resistance in obesity." (PMID 31577826, 2019). "Secondly, the inflammatory environment from IL-6 overexpression from hypomethylation induces obesity hence leads to higher blood pressure as part of obesity-associated metabolic syndrome." (PMID 31908586, 2019). "Both PAH and obesity are regarded as inflammatory conditions associated with induction of cytokines (e.g. IL-6 and TNF-α) and pro-inflammatory enzymes (e.g. iNOS)." (PMID 30689673, 2019). "Our findings suggest that visfatin and IL-6 levels in GCF are associated with the pathogenesis of obesity and periodontitis." (PMID 31365708, 2019). "Obesity in cats has been associated with alterations in adipokines including: adiponectin, interleukin-6 (IL6), and tumor necrosis factor-α (TNFα)." (PMID 31492181, 2019). "The JAK/STAT pathway is implicated in obesity and chronic metabolic diseases, serving as an important adjuster for growth factor hormones and cytokines of leptin, IL-6, and IFN-γ." (PMID 31344867, 2019).
Obesity (continued). "Obesity is associated with increased expression of proinflammatory cytokines such as IL-6, TNFα, and IL-1β in adipose tissue." (PMID 31828157, 2019). "Obesity is associated to a low-grade inflammation that alters the expression of adiponectin, leptin, IL-6, Monocyte Chemotactic Protein 1 (MCP1), TRAIL, LIGHT/TNFSF14, OPG, and TNFα." (PMID 31130918, 2019). "IL-6 is the most abundant cytokine and has frequently been uncovered in the context of obesity-associated metabolic disorders." (PMID 30736731, 2019). "Pro-inflammatory adipokines such as leptin, Tumor Necrosis Factor-alpha (TNF-α), interleukin (IL)-6, IL-1, IL-8, and resistin are increased in obesity and are associated with insulin resistance, type 2 diabetes and cardiovascular disorders." (PMID 31475003, 2019). "Obesity and psoriasis share common pathogenic mechanisms, including increased proinflammatory cytokines (IL-1, IL-6, TNF-α, and adiponectin)." (PMID 31275060, 2019). "Specifically, the researchers reported that plasma DGLA was positively associated with IL-6 only in participants with obesity." (PMID 31141526, 2019). "IL-6 is the most widely studied exercise-regulated cytokine and is associated with obesity and insulin resistance; but it is also highly produced and secreted after exercise, enhancing insulin action and other metabolic processes." (PMID 31590286, 2019). "We concluded that obesity is the main exposure positively associated with IL-6 and CRP and inversely associated with adiponectin (mainly in females)." (PMID 31071114, 2019). "Macrophages can clear dead adipocytes that induce the expression of IL1β and IL6, so their clearance was associated with the inhibition of inflammation in obesity." (PMID 31191541, 2019). "Based on the multifaceted roles of IL-6, M2-like macrophages and γδ T cells in obesity and associated cancers, the importance of these as either biomarkers or mediators of clinical treatments remains tentative." (PMID 31379820, 2019). "In this particular case, obesity is a known risk factor for asthma, both conditions inducing an elevation of the pro-inflammatory cytokines concentration, especially IL-6 in blood." (PMID 30605486, 2019). "The principle of this statement is that low-grade inflammation caused by CRP and IL-6 mediates obesity, inflammation, insulin resistance and cardiovascular diseases." (PMID 30624536, 2019). "IL-6 also contributes to counterbalance obesity-associated inflammation by favoring macrophage polarization towards the M2 phenotype, both in the liver and adipose tissue." (PMID 30818779, 2019). "Regarding the relationship between obesity and the inflammatory and iron markers, pgBMI was positively associated to IL-6, leptin, and CRP." (PMID 30909605, 2019). "When restricted to obesity-associated cancers, IL-6 remained significantly associated with increased risk of cancer mortality (HR: 3.33, 95% CI: 1.61–6.87), but none of the other biomarkers remained significant in adjusted models." (PMID 31448052, 2019). "The study aims to determine salivary IL-6 and leptin as obesity associated inflammation markers using a new non-invasive method with clinical applications in case of children diagnosed with overweight and obesity." (PMID 30605486, 2019). "Pro-inflammatory cytokines, such as tumor necrosis factor alpha (TNF-α) and interleukin six (IL-6), have often been associated with obesity." (PMID 31141526, 2019). "Obesity and diabetes were associated with increased leptin and decreased adiponectin plasma levels, higher protein expression of leptin and IL-6 in SAT, and higher visfatin protein expression in EAT." (PMID 31533725, 2019). "In this prospective cohort study of African-American and White participants within the REGARDS cohort, higher levels of baseline circulating IL-6 was associated with higher overall and obesity-associated cancer mortality." (PMID 31448052, 2019).